SPON1 (spondin 1)
Diseases named in the same sentence as SPON1 in open-access papers (continued):
Sharing a sentence is not in itself a finding about the gene and the disease.
tumor (continued). "Although our findings support that SPON1+ TIMs can upregulate diverse species of collagen production through tumor cell LRP8 expression, we then determined whether CAFs can also produce collagen via a SPON1/LRP8 axis." (PMID 38716730, 2024). "To evaluate whether SPON1 signaling through LRP8 can induce TGF-β1 activation, we evaluated several of our tumor models and spheroids for SMAD2 phosphorylation." (PMID 38716730, 2024). "Importantly, our work uncovers an intercellular SPON1/LRP8/TGF-β axis that bridges the gap between SPON1+ TIMs and ECM remodeling, while also identifying tumor cells as a key producer of collagen." (PMID 38716730, 2024). "Positivity within tumors was significantly correlated with collagen IV and vimentin expression, suggesting a role of SPON1 in the reorganization and remodeling of tumor extra cellular matrix (ECM) (data not shown)." (PMID 24133572, 2013).
infection (1 paper, 2020). The state of being infected such as from the introduction of a foreign agent such as serum, vaccine, antigenic substance or organism. "We observed that SPON1 reduced Aβ levels both in the co-culture of mouse iNSC-Spon1 and mouse N2a cells and in human SPON1 infection into human 293T-APP cells." (PMID 32455709, 2020).
kidney disease (1 paper, 2014). "The role of Spon1 in kidney disease requires further studies." (PMID 24667548, 2014). "In particularly, we were interested in Spon1, which has never been studied in kidney disease." (PMID 24667548, 2014).
SPON1 also shares sentences with these, for which no sentence is quoted: atrial fibrillation (3 papers); osteoarthritis (3); breast carcinoma (2); chronic kidney disease (2); brain ischemia (1); colon cancer (1); craniosynostosis (1); eye disorder (1); familial Alzheimer disease (1); gastric adenocarcinoma (1); glaucoma (1); Hepatic fibrosis (1); hyperlipidemia (1); idiopathic pulmonary fibrosis (1); immune system disease (1); melanoma (1); metastatic cancers (1); myocardial infarction (1); nephrotic syndrome (1); neurodegenerative disease (1); osteoporosis (1); ovarian tumor (1); renal carcinoma (1); thyroid cancer (1); tuberculosis (1); urothelial carcinoma (1).